CIMIP2A (ciliary microtubule inner protein 2A)
Description:
Microtubule inner protein (MIP) part of the dynein-decorated doublet microtubules (DMTs) in flagellum axoneme. Binds to the intra-tubulin interfaces.
Synonyms: FAM166A; HSD46
Tractability: No criterion of Open Targets' tractability assessment is met for any kind of drug.
Gene: Protein-coding gene on chromosome 9 (137,243,584 to 137,247,770, reverse strand). Ensembl gene ENSG00000188163.
Subcellular location: Cytoplasm, cytoskeleton, flagellum axoneme
Subcellular location (Human Protein Atlas): End piece; Mid piece; Principal piece
Gene Ontology:
Molecular function: protein binding
Biological process: flagellated sperm motility
Cellular component: ciliary basal body; nucleus; axonemal A tubule inner sheath; sperm flagellum; cilium; microtubule cytoskeleton
Genetic constraint (gnomAD): Loss-of-function variants: 41 observed, 36.89 expected, observed/expected ratio (o/e) 1.11, 90% interval 0.87 to 1.44. The synonymous counts are far from expectation, so gnomAD's model fits this gene poorly and the ratio says little. Missense variants: 588 observed, 418.35 expected, observed/expected ratio (o/e) 1.41, 90% interval 1.31 to 1.5. Synonymous variants: 205 observed, 163.66 expected, observed/expected ratio (o/e) 1.25, 90% interval 1.12 to 1.41.
Homologues: Orthologues: chimpanzee CIMIP2A (97% identical), macaque CIMIP2A (91% identical), guinea pig CIMIP2A (79% identical), mouse Cimip2a (78% identical), rat Cimip2a (78% identical), dog CIMIP2A (77% identical), pig CIMIP2A (76% identical).